CST6 (cystatin E/M)
Diseases named in the same sentence as CST6 in open-access papers (continued):
Sharing a sentence is not in itself a finding about the gene and the disease.
preeclampsia (2 papers, 2025 to 2026). Preeclampsia is a hypertensive disorder of pregnancy that is characterized by new-onset hypertension with proteinuria presenting after 20 weeks of gestation, and depending on mild or severe forms may initially present with severe headache, visual disturbances, and hyperreflexia. "Placental CST6 mRNA expression was significantly increased in 78 pregnancies complicated by early-onset preeclampsia (delivering at < 34 weeks’ gestation) relative to 30 gestation matched controls (P < 0.0001)." (PMID 40234537, 2025). "Circulating CST6 was increased in 35 pregnancies complicated by early-onset preeclampsia (< 34 weeks’ gestation) relative to 27 gestation matched controls (P = 0.0261), and LGMN levels remained unchanged." (PMID 40234537, 2025). "CST6 expression was significantly increased 5.65-fold in placenta from patients with early-onset preeclampsia, relative to controls (P < 0.0001)." (PMID 40234537, 2025). "CST6 expression and levels in circulation are increased in preeclampsia whilst overall, LGMN is decreased relative to gestation matched controls." (PMID 40234537, 2025). "There was a significant increase in the CST6/LGMN ratio in patients who went on to develop preeclampsia (23.19 [IQR, 4.31–59.34], P = 0.0003), compared to those delivering at term without preeclampsia (12.09 [IQR, 3.50–72.87])." (PMID 40234537, 2025). "Following confirmation of dysregulated CST6 and LGMN expression in the placenta of women with early-onset preeclampsia, we next sought to investigate circulating levels of CST6 and LGMN." (PMID 40234537, 2025). "The increase in CST6 in maternal plasma correlates with the elevated placental mRNA expression observed in women with early-onset preeclampsia." (PMID 40234537, 2025). "We observed a modest increase in CST6 mRNA expression in early-onset preeclampsia compared to preterm controls." (PMID 40234537, 2025). "In non-oncological contexts, CST6 maintains skin barrier homeostasis, mediates preeclampsia pathosis, and is associated with conditions such as pulmonary fibrosis." (PMID 41907140, 2026). "This suggests that high circulating CST6 may exacerbate the maternal endothelial dysfunction observed in preeclampsia." (PMID 40234537, 2025). "Given their close relationship, this may suggest elevated levels of CST6 in preeclampsia could contribute to the development and progression of preeclampsia via similar mechanisms to that of Cystatin C. However, these mechanisms require further investigation." (PMID 40234537, 2025). "While CST6 has been reported to contribute to both tumour suppression and growth outside of pregnancy, its role in pregnancy and preeclampsia remains largely unknown." (PMID 40234537, 2025). "Thus, significantly increased CST6 mRNA expression is accompanied by significantly reduced LGMN mRNA expression in placentas from women with early-onset preeclampsia." (PMID 40234537, 2025). "The performance of CST6 and LGMN either alone, or in combination as biomarkers for preeclampsia prediction after 36 weeks’ gestation was modest." (PMID 40234537, 2025). "A significant strength of this study in the use of well characterised patient cohorts to confirm the dysregulation of CST6 and LGMN in preeclampsia." (PMID 40234537, 2025). "As CST6 is increased in maternal circulation in preeclampsia, we exposed HUVEC cells to recombinant CST6." (PMID 40234537, 2025). "Our snRNA-seq analysis revealed similar expression profiles for both CST6 and LGMN between early-onset preeclampsia and term controls." (PMID 40234537, 2025). "We confirmed that CST6 and LGMN are significantly dysregulated in both placenta and circulation in women with preeclampsia, compared to controls." (PMID 40234537, 2025). "Using snRNA-seq analysis, we conducted an additional validation of specific cell type expression of CST6 and LGMN in the placenta of both early-onset preeclampsia and controls." (PMID 40234537, 2025).
preeclampsia (continued). "This study aimed to characterise CST6 and one of its high affinity targets, Legumain (LGMN), in preeclampsia and assess its biomarker potential by measuring levels in maternal circulation." (PMID 40234537, 2025). "In this study, we sought to characterise CST6 and LGMN in preeclampsia." (PMID 40234537, 2025). "In this study, we aimed to characterise CST6 and LGMN in the placenta and in preeclampsia." (PMID 40234537, 2025). "Our findings indicate an inverse relationship between CST6 and LGMN in preeclampsia." (PMID 40234537, 2025). "In preeclampsia, low levels of LGMN and further inhibition of LGMN by elevated levels of CST6 may disrupt placental development." (PMID 40234537, 2025). "Thus, while we confirm dysregulated circulating CST6 and LGMN preceding diagnosis of term preeclampsia, the AUC for either molecule alone, or as a ratio, were modest." (PMID 40234537, 2025). "Overall, our findings demonstrate that CST6 and LGMN are dysregulated in preeclampsia." (PMID 40234537, 2025). "Unlike CST6, LGMN mRNA expression increased with gestational age and with increasing fetal birth weight in the preeclampsia group." (PMID 40234537, 2025). "At 36 weeks’ gestation, circulating CST6 was significantly increased (P = 0.001), while LGMN was significantly decreased (P = 0.0135) in 21 pregnancies preceding diagnosis of preeclampsia at term, compared to 184 pregnancies that did not develop preeclampsia." (PMID 40234537, 2025).
squamous cell carcinoma (2 papers, 2010 to 2025). A carcinoma arising from squamous epithelial cells. "The expression level of CST6 in the metastatic foci of squamous cell carcinoma of the oral cavity is 40 times that in the primary lesion." (PMID 40745648, 2025). "Interestingly, basal cell and squamous cell carcinomas were found to express cystatin E/M only in well differentiated cells." (PMID 20074384, 2010).
acne (1 paper, 2025). An inflammatory process of the sebaceous glands which is characterized by comedones, nodules, papules and/or pustules on the skin. "For example, cystatin E/M (CST6), endonuclease, poly(U) specific (ENDOU), and galanin (GAL) were associated with acne in our study (e.g. galanin: beta = 0.27 s.d." (PMID 41068475, 2025).
bladder cancers (1 paper, 2025). "Our results revealed that CST1/CST2/CST6 genes were significantly upregulated, whereas CST3/CTS7 genes were downregulated in bladder cancers." (PMID 40747123, 2025). "In this study, our results from benign bladder tissues and cancer cell lines showed that CST3, CST6, CSTA, and CSTB were the predominant isoforms out of the 14 family members expressed by bladder cancer cells." (PMID 40747123, 2025). "In bladder cancer tissues, CST1, CST2, CST6, CSTA, and CSTB were significantly upregulated, while CST3 and CST7 were downregulated compared to benign tissues." (PMID 40747123, 2025). "CST6, CSTA, and CSTB were upregulated, while CST3 and CST7 were downregulated in bladder cancer tissues." (PMID 40747123, 2025).
brain tumors (1 paper, 2021). "It was found that CST6 promoter was hypomethylated in normal brain samples, albeit most primary brain tumors demonstrated deficient cystatin M/E expression, in agreement with CST6 promoter hypermethylation." (PMID 33919854, 2021).
cervical tumors (1 paper, 2021). "The loss of expression of cystatin M/E that is associated with CST6 inactivation by somatic mutations and promoter hypermethylation was also detected in primary cervical tumors." (PMID 33919854, 2021).
colorectal cancer (1 paper, 2021). A primary or metastatic malignant neoplasm that affects the colon or rectum. "The expression of CST6 was upregulated in BLCA, COAD, and READ for TCGA datasets, while no significantly differently expressed was observed in bladder and colorectal cancer for the MMDs." (PMID 34603393, 2021).
endothelial dysfunction (1 paper, 2025). In vascular diseases, endothelial dysfunction is a systemic pathological state of the endothelium (the inner lining of blood vessels) and can be broadly defined as an imbalance between vasodilating and vasoconstricting substances produced by (or acting on) the endothelium. "Administering recombinant CST6 to endothelial cells enhanced markers of endothelial dysfunction and LGMN expression in the presence of TNFα." (PMID 40234537, 2025). "Taken together, recombinant CST6 may further amplify endothelial dysfunction in the presence of inflammation." (PMID 40234537, 2025). "Finally, we sought to identify the source of circulating CST6 and LGMN and investigate the effects of recombinant CST6 on endothelial dysfunction." (PMID 40234537, 2025).
head and neck squamous cell carcinoma (1 paper, 2021). A squamous cell carcinoma that arises from any of the following anatomic sites: lip and oral cavity, nasal cavity, paranasal sinuses, pharynx, larynx, and salivary glands. "Moreover, the patients with HPV infection showed a lower expression level of CST6 in head and neck squamous cell carcinoma (HNSC), and the patients with metastasis status showed a lower expression in skin cutaneous melanoma (SKCM)." (PMID 34603393, 2021).
hepatocellular carcinoma (1 paper, 2021). A malignant tumor that arises from hepatocytes. "Survival analysis indicated that CST6 correlated with the OS and recurrence-free survival (RFS) of patients with hepatitis B virus-related hepatocellular carcinoma (HBV-related HCC)." (PMID 33919854, 2021).
kidney damage (1 paper, 2025). "This relationship could indicate that CST6 might be involved in kidney injury or dysfunction, potentially serving as a marker for kidney damage or impairment." (PMID 40004202, 2025).
metastatic disease (1 paper, 2010). "Our initial interest in cystatin E/M arose from microarray studies comparing the gene expression profiles of primary and metastatic melanoma, where expression of the cystatin E/M gene (CST6) was observed in normal skin and thin primary tumors, but not in thicker primaries or metastatic disease." (PMID 20074384, 2010).
metastatic melanoma (1 paper, 2010). A melanoma that has spread from its primary site to another anatomic site. "In a previous study comparing the gene expression profiles of primary and metastatic melanoma, it was shown that CST6 gene expression progressively decreases during disease progression." (PMID 20074384, 2010). "We have identified several cell lines derived from both primary and metastatic melanoma that secrete cystatin E/M." (PMID 20074384, 2010). "In summary, we have shown that cystatin E/M acts as a regulator of proteolytic activity of legumain and suppressor of invasion in metastatic melanoma." (PMID 20074384, 2010). "Furthermore, there was a significant decrease in CST6 expression between primary and metastatic melanoma when analyzed by microarray and quantitative RT-PCR." (PMID 20074384, 2010).
oropharyngeal squamous cell carcinoma (1 paper, 2010). "It has been reported that cystatin E/M is up-regulated during the progression from primary to metastatic oropharyngeal squamous cell carcinoma." (PMID 20074384, 2010).
ovarian serous cystadenocarcinoma (1 paper, 2021). A malignant serous cystic epithelial neoplasm arising from the ovary. "We found that the expression of CST6 was significantly different in CESC, ovarian serous cystadenocarcinoma (OV), pancreatic adenocarcinoma (PAAD), and SKCM." (PMID 34603393, 2021).
serous ovarian cancer (1 paper, 2021). "In the present study, we examined the methylation status of six gene promoters (BRCA1, CST6, MGMT, RASSF10, SLFN11 and USP44) in high-grade serous ovarian cancer (HGSOC)." (PMID 35008168, 2021).
Systemic Lupus Erythematosus Disease (1 paper, 2023). "There was also a positive correlation between CST6 with Systemic Lupus Erythematosus Disease Activity Index (SLEDAI) and CST6 with albumin in CSF." (PMID 37684700, 2023).
uterine carcinosarcoma (1 paper, 2021). A usually aggressive malignant neoplasm arising from the uterine corpus and less often the cervix. "The expression of CST6 was related to the stage of BLCA, COAD, kidney papillary cell carcinoma (KIRP), OV, READ, SKCM, THCA, and uterine carcinosarcoma (UCS)." (PMID 34603393, 2021).
tumor (49 papers, 2007 to 2025). "The GSEA analysis of GEO public database (GSE13579) indicated that CST6 is associated with lymphatic vessel formation during tumor metastasis." (PMID 40745648, 2025). "Epigenetic silencing of CST6 has been widely observed in cancers 15, 28, 29 and it has long been implicated as a tumor suppressor." (PMID 34815788, 2021). "We investigated four candidate genes, three of which, cystatin E/M (CST6) and the micro RNA genes miR-9-1 and miR-124-3, were identified recently with tumor-specific CGI hypermethylation and a possible association with the prognosis of RCC patients." (PMID 24633192, 2014). "Only increased expression of cystatin CST6 (implicated in tumor suppression) and of the dehydrogenase HSD17B2 (involved in sterol metabolism) were common to both PHKs and HaCaT." (PMID 23702334, 2013). "Cst6 encodes cystatin M/E, an inhibitor of the cathepsin L cysteine protease, which has been implicated in epidermal differentiation and tumor suppression." (PMID 21949838, 2011). "The methylation status of CST6 gene encoding cystatin M was evaluated using methylation-specific polymerase chain reaction (PCR) in formalin-fixed paraffin-embedded tissues from 292 participants and using pyrosequencing in fresh-frozen tumor and matched normal tissues from 51 IBC patients." (PMID 21092257, 2010). "Our qRT-PCR validation confirmed the significant upregulation of CST6 in GC tumor tissues compared to adjacent normal tissues (p < 0.05), supporting its potential as a diagnostic marker." (PMID 40978044, 2025). "The expression heterogeneity of CST6 across different GC studies and tumor types suggests its potential as a novel target for further research." (PMID 40978044, 2025). "In summary, this work presents a rational approach to engineering BCMA–CST6–CAR-T cells that can effectively target MM tumor cells in vitro and in vivo and that can release large amounts of CST6 protein, which significantly suppresses osteolytic lesions in MM." (PMID 37883186, 2024). "The other cluster, M4, mainly appeared in tumor-bearing mice and was dramatically decreased after CST6 protein treatment." (PMID 35881476, 2022). "Cystatin E/M (CST6), a representative cysteine protease inhibitor, has been well appreciated as a tumor-promoting and tumor-suppressing agent and is pursued as an epigenetically therapeutic target in special cancer types." (PMID 36389725, 2022). "The silencing of CST6 expression in tumor oral cancer cell line increases both invasion and motility, but also renders metastatic MDA-686Ln cells hyperproliferative." (PMID 33919854, 2021). "Functional analysis validated the suppressing roles of CST6 in tumor invasion and breast-to-bone metastasis." (PMID 34815788, 2021). "The expression of CST6 was significantly higher in SKCM primary tumor tissues than that of metastatic samples." (PMID 34603393, 2021). "Nevertheless, our study revealed a new role of CST6 to regulate tumor stroma instead of cancer cells." (PMID 34815788, 2021). "Tumor samples were divided into high-expression and low-expression groups based on CST6 expression for each TCGA tumor type." (PMID 34603393, 2021). "Given that SKCM has the maximum number of metastatic samples in TCGA, we next compared the expression level of CST6 between metastasis samples and primary tumor tissues." (PMID 34603393, 2021). "Cystatin E/M (CST6), a representative cysteine protease inhibitor, plays both tumor-promoting and tumor-suppressing functions and is pursued as an epigenetically therapeutic target in special cancer types." (PMID 34603393, 2021). "To further investigate the function of CST6 across cancer types, we first obtained 500 CST6-related genes for all TCGA tumor samples from the GEPIA2 “Correlation Analysis” module." (PMID 34603393, 2021). "To extend the expression pattern of CST6 with tumor pathological information, we applied the “Stage Plot” and “Subtype Filter” functions of GEPIA2." (PMID 34603393, 2021).
tumor (continued). "Treatment with a DNA demethylating agent (5-aza-2′-deoxycytidine, 5-aza-dC) reactivated CST6 transcription and expression, substantiating that cystatin M/E is an epigenetically-inactivated tumor suppressor gene." (PMID 33919854, 2021). "Collectively, these data indicated that CST6 directly targets on cells of osteoclast lineage, instead of tumor cells, to regulate osteoclastogenesis." (PMID 34815788, 2021). "Taken together, all these results suggest that CST6 was related to epithelial cell infiltration and tumor EMT process." (PMID 34603393, 2021). "For example, lncRNA AL121899.1 and PCG CST6 were positively correlated in normal samples (rNormal = .856), but negatively correlated with tumour samples (rTumour = −.419)." (PMID 32164040, 2020). "On the contrary, the combination treatment up‐regulated expression of several known tumour suppressor genes like CST6, TFPI2, GSTP1 and several others." (PMID 32720467, 2020). "All five genes in the module (AL121899.1, GFOD2, SPINK8, C2orf54 and CST6) were down‐regulated and lost positive correlations with their neighbours in tumour samples." (PMID 32164040, 2020). "Five genes (BNC1, COL14A1, CST6, PDLIM4, and SFRP1) demonstrated frequent tumor-specific promoter region methylation (>30%), associated with transcriptional silencing." (PMID 28326264, 2015). "Primary tumor tissues from 18 patients receiving targeted therapy were examined retrospectively using quantitative methylation-specific PCR analysis of CST6, LAD1, hsa-miR-124-3, and hsa-miR-9-1 CpG islands." (PMID 24633192, 2014). "CST6 is an important tumor suppressor in multiple tissues, acting as a dual protease inhibitor of both papain-like cathepsins and asparaginyl endopeptidases (AEPs) such as Legumain (LGMN)." (PMID 24742492, 2014). "The prevalence of CST6 loss and LGMN hyperactivation across many tumor types therefore represents an exciting opportunity for the development of novel targeted therapies." (PMID 24742492, 2014). "Ectopic expression of CST6 suppressed metastasis in animal studies, whereas CST6 knockdown increased tumor aggressiveness." (PMID 24713112, 2014). "In this study, our group successfully demonstrated that treatment with recombinant CST6 (rmCST6) and zoledronic acid (ZA) in MM tumor-bearing mice and ovariectomy (OVX)-induced hyper-bone resorptive mice significantly reduced bone loss and decreased OVX-induced inflammatory cytokine expression." (PMID 40075680, 2025). "Furthermore, CST6 neutralizing antibody significantly reduced circFAM13B-transduced tumor burden in lymph nodes, indicating that blocking CST6 signaling abrogates circFAM13B-induced lymphatic metastasis in vivo." (PMID 40745648, 2025). "Paracrine CST6 may promote tumor escape from immune surveillance by preventing the protease-dependent presentation of MHC class II molecules on the cell surface or preventing T cell lysosomal protease-mediated cell death." (PMID 35881476, 2022). "The relationship between CST6 and tumor microenvironment was also explored." (PMID 34603393, 2021). "CST6 could serve as a biomarker for tumor diagnosis and play a dual functional effect across cancer types." (PMID 34603393, 2021). "We next explored the critical efficiency of CST6 in the survival of tumor patients." (PMID 34603393, 2021). "However, there has been limited research that comprehensively explored the relationship between CST6 and tumor microenvironment in pan-cancer level." (PMID 34603393, 2021). "We further evaluated whether there is any association between SOX17, CST6, and BRMS1 promoter methylation in CTC, ctDNA and corresponding primary tumours and the clinical outcome of patients." (PMID 29069768, 2017). "First, the potential LAD1 and CST6 DNA methylation-based markers were measured in tumor cells, which directly exhibit tumor characteristics that may represent drivers of resistance and biological aggressiveness." (PMID 24633192, 2014).